SLC22A5 (solute carrier family 22 member 5)
Diseases named in the same sentence as SLC22A5 in open-access papers (continued):
Sharing a sentence is not in itself a finding about the gene and the disease.
hypertrophic cardiomyopathy (1 paper, 2024). A condition in which the myocardium is hypertrophied without an obvious cause. "Still, the literature contains studies on the coincidence of PCD and hypertrophic cardiomyopathy in SLC22A5 variants." (PMID 38166572, 2024). "In the present study, we detected a novel pathogenic variant, SLC22A5 (NM_003060.4), c.821G > A: p.Trp274Ter, in an Iranian family with early manifestations of hypertrophic cardiomyopathy and metabolic abnormalities, corresponding to the clinical and paraclinical symptoms of PCD." (PMID 38166572, 2024). "In conclusion, the paucity of information on PCD patients with hypertrophic cardiomyopathy involvement in SLC22A5 variants warrants future studies to reveal the role of this gene in the development of coincident PCD and hypertrophic cardiomyopathy." (PMID 38166572, 2024). "Research on the SLC22A5 gene is limited to patients with hypertrophic cardiomyopathy." (PMID 38166572, 2024).
kidney failure (1 paper, 2017). An acute or chronic condition that is characterized by the inability of the kidneys to adequately filter the blood. "Eight genes related to kidney toxicity, including kidney failure (CASP1, FCGR2A, FCGR2B, TLR2, TLR4, P = 0.003), damage of renal tubule (TLR2, TLR4, P = 0.01), proximal tubular toxicity (CTSS, LYZ, SLC22A5, P = 0.007) and their expression across 6 datasets were not confounded by tissue types." (PMID 28051114, 2017).
multiple sclerosis (1 paper, 2023). A progressive autoimmune disorder affecting the central nervous system resulting in demyelination. "However, looking into our phenotypic data we can verify that CTD (SLC22A5), Parkinson ́s disease (LRPPRC), multiple sclerosis (IL4R), 3-MCCD (MCCC1), and different cancer types (FANCE, MAD1L1 and CD46) have been reported by the participants." (PMID 36404349, 2023).
ovarian carcinoma (1 paper, 2016). A malignant neoplasm originating from the surface ovarian epithelium. "The HCMECs express relatively low levels of the high-affinity OCTN1/SLC22A4 and OCTN2/SLC22A5 transporters and relatively high levels of the high-affinity OCT1/SLC22A1 and low-affinity OCT2/SLC22A2 transporters compared to the HBMECs and A2780 ovarian carcinoma cells." (PMID 27543060, 2016).
Parkinson ́s disease (1 paper, 2023). "These include variants within disease-causing genes for common monogenetic diseases in the Faroese population, such as CTD (SLC22A5), as well as complex disease, such as Parkinson ́s disease (LRPPRC)." (PMID 36404349, 2023).
psoriasis (1 paper, 2015). An autoimmune condition characterized by red, well-delineated plaques with silvery scales that are usually on the extensor surfaces and scalp. "SLC22A5 has previously been reported to be associated with IBD25, whereas previous psoriasis reports relating to chromosome 5q31 have focused on variants mapping to the IL13 gene." (PMID 25651891, 2015).
rhabdomyosarcoma (1 paper, 2024). A rare aggressive malignant mesenchymal neoplasm arising from skeletal muscle. "The BCR::ABL1-positive CML cell line KCL-22 and the rhabdomyosarcoma cell line HTB-153 express SLC22A5 mRNA at comparable levels." (PMID 39182842, 2024).
rosacea (1 paper, 2025). A chronic erythematous skin disorder that affects the face. "In summary, we confirmed the causal relationship between IRF1 and SLC22A5 and the risk of rosacea using MR and Bayesian colocalization analysis." (PMID 40635520, 2025). "In this research, we identified an important causal relationship between two druggable genes, IRF1 and SLC22A5, and the development of rosacea." (PMID 40635520, 2025). "Our research provides new genetic evidence for the protective effect of SLC22A5 in rosacea; the MR results of blood showed that the expression of SLC22A5 was negatively correlated with the risk of rosacea (OR = 0.79, p = 5.08E‐29)." (PMID 40635520, 2025). "Second, due to the lack of genetic studies at the protein level, we were unable to confirm whether the protein quantitative trait loci for IRF1 and SLC22A5 were associated with the risk of rosacea." (PMID 40635520, 2025). "The GEO data sets verified that the expression of SLC22A5 was downregulated in patients with rosacea (adj." (PMID 40635520, 2025). "Molecular docking revealed that Tretinoin, which is known to improve rosacea by anti‐inflammatory mechanisms, binds SLC22A5 with high affinity (−6.51 kcal/mol)." (PMID 40635520, 2025). "MR and SMR analyses identified IRF1 and SLC22A5 as druggable genes for rosacea, with Bayesian colocalization strongly supporting shared causal variants." (PMID 40635520, 2025). "Through the comprehensive analysis of rosacea of three tissues, SMR analysis identified three druggable genes in human blood that were causally associated with rosacea‐related traits (p‐FDR < 0.05), including P4HA2, IRF1, and SLC22A5." (PMID 40635520, 2025). "By analyzing the GSE65914 data sets, we evaluated the expression of IRF1 and SLC22A5 genes in the three major subtypes of rosacea." (PMID 40635520, 2025). "This study identified IRF1 and SLC22A5 as potential drug targets for the treatment of rosacea, and their significant therapeutic potential provides a critical foundation for the development of targeted therapies." (PMID 40635520, 2025). "GEO data sets confirmed significant upregulation of IRF1 and downregulation of SLC22A5 in rosacea patients." (PMID 40635520, 2025). "Finally, although our MR Analysis identified IRF1 and SLC22A5 as potential drug targets for rosacea, these findings remain hypothetical at this time and require further validation in experimental models." (PMID 40635520, 2025). "HEIDI tests showed that the association between expression levels of IRF1, SLC22A5, and rosacea was not caused by linkage imbalance (p > 0.01)." (PMID 40635520, 2025).
sickle cell disease (1 paper, 2022). Sickle cell anemias are chronic hemolytic diseases that may induce three types of acute accidents: severe anemia, severe bacterial infections, and ischemic vasoocclusive accidents (VOA) caused by sickle-shaped red blood cells obstructing small blood vessels and capillaries. "Bantu, Afro-related ethnolinguistic cultural groups, and Latin America have a similar low proportion of pathogenic variants in most of the sickle cell disease-specific genes, except in MY O 7B, CPS1, COL6A3, MTRR, SLC22A5, ABCC1, and RPL3L." (PMID 35812734, 2022).
Stroke (1 paper, 2020). Sudden impairment of blood flow to a part of the brain due to occlusion or rupture of an artery to the brain. "For the extreme contrast of “stroke” versus “long survivor”, only four gene sets – SERPINC1, SLC22A5, CACNA1H, and SLC4A1 [MIM: 109270] – were significant." (PMID 32898326, 2020).
cancer (25 papers, 2010 to 2026). A tumor composed of atypical neoplastic, often pleomorphic cells that invade other tissues. "There are reports about oncogenetic variants in the SLC22A4 (OCTN1) and SLC22A5 (OCTN2) genes to be linked to prolonged time to progression or optimal response to imatinib treatment in different cancers." (PMID 32806706, 2020). "All of the results suggest that MTs of ADPGK, PCGF6, PKP2, NUP93 and SLC22A5 can be the driver mutations controlling the cancer metastasis via affecting the EMT pathways where Snail, Claudin-1 or ZEB1 is involved." (PMID 27625789, 2016). "We identify driver mutations in ADPGK, NUP93, PCGF6, PKP2 and SLC22A5, which are verified to enhance cancer cell migration and prompt metastasis with in vitro experiments." (PMID 27625789, 2016). "SLC22A5 was among the mutated genes enhancing cancer cell migration." (PMID 31861504, 2019). "Since SLC6A14 can also transport L-carnitine, albeit with a lower affinity than OCTN2/SLC22A5, similar nanoparticles have been shown to bind to and utilize both transporters in various cancer cell lines." (PMID 36770817, 2023). "The link between cancer predisposition and genetic variants of SLC22A1 and SLC22A5 is poorly explored." (PMID 36077209, 2022). "Bearing in mind that CPT1 requires carnitine for its function, it is worth taking a closer look at SLC22A5, a transporter that delivers carnitine into the cells, in the context of cancer." (PMID 31861504, 2019). "This points to a need for a deeper understanding of the role played by carnitine, SLC22A5 and fatty acid oxidation in both cancer and in the brain—fields that up until recently have been under-researched." (PMID 31861504, 2019). "On the other hand, SLC22A5 can also transport several chemotherapeutics used in clinics, leading to cancer cell death." (PMID 31861504, 2019). "Currently, there are anti-cancer drugs on the market with the purpose of inhibiting SLC22A5." (PMID 32362913, 2020). "Interestingly, however, there are also clinically used anti-psychotic drugs (amisulpride) and anti-cancer drugs such as etoposide, oxaliplatin and imatinib that are taken up by cells via SLC22A5." (PMID 31861504, 2019). "Since activators of PKC, e.g., phorbol esters, are tumor promoters, while PP2A is considered to be a tumor suppressor, such comprehensive regulation of SLC22A5 may have implications in pathological states, in particular in cancer." (PMID 31861504, 2019).
tumor (14 papers, 2010 to 2026). "Differential hypomethylation of known regulatory elements such as the DNA replication initiation site located in the first intron of DNMT1 gene (A-8 HMR) and the estrogen receptor binding sites within intron 2 of SLC22A5 (B-5 HMR) were also observed in tumor cells." (PMID 25706888, 2015). "Interestingly, SLC22A5 has also been implicated in pivaloyl-carnitine transport; therefore, it is probable that the pivaloyl-carnitine metabolite of [18F]FPIA is transported from the systemic circulation into tumor cells via SLC22A5." (PMID 34356874, 2021). "While multiple comparisons had no DE genes in the entire expressed gene list (i.e., Stage III vs. Stage IV), there were 6 DE SLC22 genes in the Tumor Size and Progression comparison in KIRC [SLC22A2, SLC22A5, SLC22A6, SLC22A11, SLC22A12, SLC22A18] (T3 v T4)." (PMID 36230695, 2022). "We assessed tumor proliferation (Ki-67) and the expression of proteins involved in lipid metabolism and transport (CPT1, SLC22A2, SLC22A5, SLS25A20) by immunohistochemistry." (PMID 34356874, 2021).
metabolic disorder (6 papers, 2019 to 2025). "PCD is a rare but well-treatable, inborn metabolic disorder caused by mutations in the SLC22A5 gene." (PMID 32276632, 2020).
gastrointestinal tumors (1 paper, 2020). "Polymorphisms rs2631367 and rs2631372, described in the SLC22A5 gene encoding OCTN2, another member of the SLC22 family involved in etoposide and imatinib transport, have been related to the prognosis of some gastrointestinal tumors treated with imatinib." (PMID 32933095, 2020).
SLC22A5 also shares sentences with these, for which no sentence is quoted: inflammatory bowel disease (6 papers); colon cancer (5); Hypoglycemia (5); genetic disease (4); hepatocellular carcinoma (4); phenylketonuria (4); autoimmune disease (3); chronic myeloid leukemia (3); diabetes (3); gastrointestinal stromal tumor (3); Obesity (3); steatosis (3); autism (2); cardiac arrhythmias (2); Encephalopathy (2); Huntington disease (2); Hyperphenylalaninemia (2); hyperuricemia (2); methylmalonic acidemia (2); 2-methylbutyryl-CoA dehydrogenase deficiency (1); abscess (1); acyl-CoA dehydrogenase deficiency (1); adult onset asthma (1); allergic disease (1); Alstrom syndrome (1); Autoimmunity (1); brain tumor (1); chronic renal failure (1); cobalamin deficiency (1); colon adenocarcinoma (1).
A further 50 diseases each share a sentence with SLC22A5 in 1 paper.